VEGFA (vascular endothelial growth factor A)
Diseases named in the same sentence as VEGFA in open-access papers (continued):
Sharing a sentence is not in itself a finding about the gene and the disease.
tumor (continued). "In this study, we found that the angiogenic response observed in zebrafish tumour xenografts has an inflammatory-driven component and that macrophages are required for effective angiogenesis within VEGFA/vegfaa-producing xenografts." (PMID 30396905, 2018). "Ang2 and the VEGFA inhibitor A2V exert anti-tumor effects in a variety of ways, including impairing tumor angiogenesis, reducing metastasis, and increasing the infiltration of pro-inflammatory macrophages." (PMID 29560266, 2018). "Correlations between HCC/NT ratios of expression levels or fractions of VEGFA isoforms and tumor clinicopathological properties." (PMID 29888133, 2018). "TNF, IL6 and ANGPT2 were expressed equally by both DLD1 and SKBR7 xenografts, whereas higher levels of IL1B, IL4, IL13 and VEGFA were found in DLD1 tumours." (PMID 29367702, 2018). "Specifically, UBE2CP3 promotes HCC cell secretion of VEGFA into the tumor microenvironment by activating the ERK/p70S6K/HIF-1α pathway; this VEGFA alters EC proliferation, migration and tube formation capacities." (PMID 29866133, 2018). "Given possible tissue specificity of VEGFA-189 functions, additional experiments on its inactivation are necessary to determine possible clinical impact of VEGFA-189 and its role in tumor development and angiogenesis." (PMID 29888133, 2018). "An increasing amount of evidence demonstrates that hypoxia inducible factor-1α (HIF-1α) is the main upstream inducer of VEGFA, which plays a key role in tumor angiogenesis." (PMID 29866133, 2018). "We observed a significant correlation of its expression with VEGFA tumor levels (p = 0.004; correlation coefficient [CC]: 0.346)." (PMID 29617404, 2018). "Other cells that assist tumor progression are recruited by growth factors such as vascular endothelial growth factor A (VEGFA), cytokines, and chemokines secreted by cancer cells and CAFs." (PMID 30211122, 2018). "Bevacizumab acts by binding to vascular endothelial growth factor A, inhibiting endothelial cell proliferation and new blood vessel formation, thereby leading to tumor vasculature normalization." (PMID 29553864, 2018). "Recently, studies have shown that many cancer cells can upregulate the expression of VEGFA to promote tumor angiogenesis." (PMID 29866133, 2018). "Previous studies have identified a critical gene dosage effect of VegfA in embryonic development and vessel homeostasis, neovascularization, and tumor growth, and potent inhibitors of VEGFR2 have been used to treat a variety of cancers." (PMID 30283071, 2018). "Our previous study and two other studies conducted at the same time suggest that miR-153 inhibits endothelial cell activity and tumor angiogenesis through downregulating the hypoxia-induced HIF1α/VEGFA pathway." (PMID 29959560, 2018). "Strikingly, VEGFA-induced tumor growth and microvascular density in Peak1−/− mice was significantly impaired compared to Peak1+/+ mice." (PMID 29872538, 2018). "We suppose that reduction of the VEGFA-189 fraction in HCC tissue can contribute to the development of more aggressive tumor phenotype." (PMID 29888133, 2018). "Our study showed that expression of both mentioned factors (HIF1A and VEGFA) was the highest et the early stage of tumor development." (PMID 30412628, 2018). "In cancers, the active growth of new blood vessels from pre-existing ones is triggered by tumour cells expressing vascular endothelial growth factor A (VEGFA) in the hypoxic microenvironment of tumour tissue." (PMID 30189837, 2018). "In particular, VEGFA (vascular and endothelial growth factor A) has a key role in breast cancer progression, through its effects on tumor angiogenesis, and also through its autocrine functions in migration, invasion and survival of breast cancer cells." (PMID 29617404, 2018). "We also determined the effect of CA and Met on the mRNA level for VEGFA in TGF-β1-stimulated C4-I cells, since VEGFA is a potent factor facilitating tumor-induced angiogenesis." (PMID 29337896, 2018).
tumor (continued). "Depletion of macrophages or VEGFA confirmed that TMEM-associated macrophages and VEGFA signaling from TAMs were essential for vascular permeability modification and tumor cell intravasation." (PMID 29599778, 2018). "A total of 50 pairs of HCC and non-tumor tissue samples were used to evaluate the VEGFA isoform spectrum using RT-PCR and quantitatively estimate changes in isoform expression using RT-qPCR." (PMID 29888133, 2018). "This is exemplified in the present study by the poor correlation of urokinase-type plasminogen activator (UPA) and vascular endothelial growth factor A (VEGFA) genes, which are both expressed by tumor cells as well as the tumor stromal cells." (PMID 30034626, 2018). "In tumor angiogenesis, especially at the early stage, the VEGFA and the ANG1/Tie2 pathways play a synergistic role." (PMID 29959560, 2018). "VEGFA-dependent angiogenesis has been shown to play a role for 4T1 tumor growth and metastasis although the effects of VEGFR2 inhibition were modest." (PMID 29721156, 2018). "Vascular endothelial growth factor A (VEGF-A), a fundamental component of angiogenesis, provides nutrients and oxygen to solid tumors, and enhances tumor cell survival, invasion, and migration." (PMID 29449553, 2018). "Third, we demonstrated that KDM4D is required for tumour angiogenesis via regulating VEGFA secretion." (PMID 30060750, 2018). "When referring to VEGFA, its overexpression in CC can enhance the growth and invasion of tumor cells." (PMID 30275981, 2018). "Pro-angiogenic macrophages promote tumor growth and invasion by secreting factors (for example, VEGFA, tumor necrosis factor alpha [TNFα], and interleukin-2 [IL-2]), eventually resulting in resistance to bevacizumab." (PMID 29560266, 2018). "PERK-ATF4 arm directly upregulates vascular endothelial growth factor A (VEGFA) and Lysosomal-Associated Membrane Protein 3 (LAMP3) thereby regulating tumour vascularity and invasion." (PMID 29545931, 2018). "While both are HIF-1 target genes, CDKN1A stalls cell cycle progression and VEGFA promotes tumor angiogenesis." (PMID 30423844, 2018). "Kim and Colleagues indeed showed that selective deletion of HIF-1a (or VEGFA) in fibroblast was enhancing tumour growth in murine mammary cancer models." (PMID 29362402, 2018). "TAMs sustain tumour angiogenesis by producing VEGFA (VEGF), the master growth factor involved in the angiogenic process." (PMID 29507865, 2018). "Specifically, EMT-TFs such as Snail and Slug, can promote blood vessel formation by inducing the expression of vascular endothelial growth factor A (VEGF-A) in subcutaneous xenograft tumor models." (PMID 29113414, 2017). "Meanwhile, we estimated tumor angiogenesis by detecting VEGFA, ESM-1 (endothelial cell specific molecule 1), and CD34 levels by ELISA assays." (PMID 28178668, 2017). "VEGFA pre-treated cells gave rise to a significant increase in lung tumor establishment as measured by tumor bioluminescence on in vivo imaging system over the next 5 weeks compared with mock-treated cells." (PMID 28504716, 2017). "In this setting, blocking VEGFA activity in murine models of EOC halts tumour growth and ascites formation." (PMID 28383032, 2017). "Limiting dilution tumor‐initiating cell assays, injecting between 100 and 100,000 cells, showed that sustained VEGFA exposure over 7 days prior to injection increased PEO1R tumor‐initiating cell abundance." (PMID 28179359, 2017). "Vascular endothelial growth factor A (VEGFA) is a major inducer of tumour blood vessel growth (tumour angiogenesis)." (PMID 27568980, 2017). "Anti-angiogenic agents inhibiting vascular endothelial growth factor A (VEGF) have been shown to normalize the tumor vasculature and improve blood flow and drug delivery." (PMID 28420326, 2017). "Full length TF promotes tumor angiogenesis by up-regulating the expression of several proangiogenic factors, including interleukin-8, chemokine (C-X-C motif) ligand-1, and vascular endothelial growth factor-A." (PMID 29017512, 2017).
tumor (continued). "Then we used the qRT-PCR to test the result of Microarray, and found VEGFA had a distinct pattern of expression in MMQ tumor stem-like cells." (PMID 28163656, 2017). "In conclusion, HCC patients with low hepatocyte growth factor (HGF), low VEGFA, high miR-26a levels or low microvessel density in tumor cells have a better prognosis with longer overall survival and time to recurrence." (PMID 28392501, 2017). "Increased TBP expression induces VEGFA expression and enhances cell migration and tumor vascularization." (PMID 28415573, 2017). "K3 HIF-2α efficiently induces HIF-2 target genes associated with tumor growth and metastasis (MMP9, PAI1, VEGFa, GLUT1) during hypoxia and low glucose stress conditions." (PMID 29281714, 2017). "The level of circulating platelets correlates with the level of serum vascular endothelial growth factor-A, playing an important role in angiogenesis for tumor progression." (PMID 29088839, 2017). "Increases in cellular TBP amounts induce VEGFA expression and secretion to enhance cell migration and tumor vascularization." (PMID 28415573, 2017). "The VEGFA status stratified on the histologic grade revealed that in the intermediate tumor grade CRCs VEGFA was amplified, polysomic or diploid in 38% (11/29), 14% (4/29) and 48% (14/29) respectively." (PMID 28403223, 2017). "HSYA from Honghua was validated to antagonize tumor angiogenesis by inhibiting the protein expression of VEGFA, MMP9 and HIF1A4." (PMID 28074863, 2017). "In the breast TME, tumor and stromal cells stimulate cytokine-mediated p38MAPK signaling that increases expression of pro-angiogenic and pro-invasive factors such as VEGFA, IL8, IL6, HBEGF, and Fibronectin." (PMID 28977919, 2017). "Since treatment of metastasis is the final therapeutic frontier, it is hoped that mechanistic insights linking VEGFA to tumor initiation and the acquisition of metastatic potential will ultimately generate new strategies for VEGF pathway-targeted intervention." (PMID 28504716, 2017). "Down-regulation of VEGFA by small interfering RNAs partially decreased cell viability of MMQ tumor stem-like cells in vitro." (PMID 28163656, 2017). "Vascular endothelial growth factor A (VEGFA) is widely accepted as the most potent stimulator of tumor angiogenesis, with anti-VEGFA therapies revealing promising outcomes in pre-clinical trials." (PMID 28008154, 2017). "Of these, KDR and FLT1 are both receptors for VEGFA, the predominant mediator of angiogenesis in tumor progression." (PMID 28388297, 2017). "Of note, CCL2- and/or VEGFA-neutralizing antibodies administered to BALB/c athymic nude mice bearing pre-established lung tumors drastically reduce tumor growth, angiogenesis, TAM accumulation, and tumor metastasis." (PMID 28851377, 2017). "When tumor cells were co-cultured with microglia, VEGFA secretion was reduced in 231BR/PTEN cells compared to 231BR/CTL cells (p < 0.05)." (PMID 28008153, 2017). "Collectively, these studies support a new role for TBP in promoting tumor vascularization through its ability to modulate VEGFA expression." (PMID 28415573, 2017). "Present data suggest that in contrast to hematologic malignancies where inactivating DNMT3A mutations reveal a tumor suppressor role, DNMT3A plays an oncogenic role as a key effector of VEGFA‐driven ovarian CSC expansion." (PMID 28179359, 2017). "The tumor‐initiating cell frequency in VEGFA‐exposed cells was 1/2,018, compared with 1/21,607 in non‐VEGFA‐exposed cells and 1/20,313 in VEGFA‐exposed cells pre‐treated with siRNA to BMI1, as calculated by L‐CalcTM Limiting Dilution Software." (PMID 28179359, 2017). "In our study, both expression and secretion of VEGFA increased obviously in tumor stem-like cells of prolactinomas." (PMID 28163656, 2017). "Vascular endothelial growth factor A (VEGF-A) is an important mediator of tumour-induced angiogenesis." (PMID 28392095, 2017).
tumor (continued). "Ex vivo exposure to VEGFA decreased tumor latency and more animals formed tumors from VEGFA‐exposed cells than from cells without VEGFA pre‐treatment." (PMID 28179359, 2017). "Mechanisms that contribute to the induction of VEGFA expression that are influenced by the tumor microenvironment have been extensively studied." (PMID 28415573, 2017). "It has been demonstrated that CD147 contributes significantly to tumor growth, metastasis and angiogenesis through stimulating the production of hyaluronan, multiple matrix metalloproteinases (MMPs) and vascular endothelial growth factor A (VEGF-A)." (PMID 28184176, 2017). "VEGFA is a key regulator of endothelial cell proliferation in most human tumours, inducing the MAPK/ERK signalling pathway." (PMID 28085225, 2017). "The animals injected with VEGFA pre-treated cells showed extensive areas of confluent tumor growth in the lungs on microscopic analysis, precluding accurate enumeration of tumor nodules." (PMID 28504716, 2017). "VEGFA as the member of VEGF family has been identified as the predominant tumor angiogenesis factor in the majority of human cancers." (PMID 28404901, 2017). "Constitutive expression of VEGFA is dictated by the genetic composition of the tumor and this is considered a critical driver of tumor initiation." (PMID 28415573, 2017). "Then we found that VEGFA mRNA increased 55.5% in human prolactinoma tumor spheres, and the expression of VEGFA protein was also significantly increased compared with the original generation cells." (PMID 28163656, 2017). "Recently, hnRNP-L was shown to bind the VEGFA mRNA and inhibit miRNA activity, thereby mediating tumor metastasis." (PMID 28088793, 2017). "Further studies are needed to clarify the role of VEGFA on the interaction of CRCs and their tumor microenvironment and to provide mechanistic insight into these observations." (PMID 28403223, 2017). "During tumor angiogenesis, de novo blood vessel formation is initiated by the unbalanced secretion of vascular endothelial growth factor A (VEGFA) by tumors and involves many of the same processes as those involved in physiological angiogenesis." (PMID 28483980, 2017). "Tumor vascularization involves a release of matrix-deposited VEGFA by MMP9 produced by various cells in the TME." (PMID 28977919, 2017). "Macrophages are important for this angiogenic switch in tumours particularly through production of vascular-endothelial growth factor A (VEGF-A) and placental growth factor (PlGF)." (PMID 28210073, 2017). "We have also demonstrated that artificially imposed hypoxia (i.e., by exposing tumor-bearing mice to a low oxygen atmosphere) can increase VEGFA expression and induce angiogenesis in the same tumor model." (PMID 29183378, 2017). "The protein expression of VEGFA decreased 32.4 and 26.6% in tumor stem-like cells and MMQ cells by siRNA silencing, respectively." (PMID 28163656, 2017). "VEGFA is an important pro-angiogenic factor for tumor progression because it promotes endothelial cell proliferation and remodels the extracellular matrix in blood vessels." (PMID 29137376, 2017). "In agreement with our findings, VEGFA was reported to be overexpressed in several different tumor types." (PMID 29104726, 2017). "Consistently, similar results were observed in the staining of proliferating cell nuclear antigen (PCNA), RICTOR and VEGFA in these tumor tissues." (PMID 28030804, 2017). "Morever, we found the level of VEGFA in culture medium supernatant of MMQ tumor sphere cells was 77.9% higher than that in MMQ cells (P < 0.01)." (PMID 28163656, 2017). "Then WB and ELISA were used to confirm the VEGFA protein level of tumor sphere cultured from both MMQ cell and human prolactinoma cell." (PMID 28163656, 2017). "In the CRCs of high tumor grade VEGFA was amplified, polysomic or diploid in 22% (2/9), 22% (2/9) and 56% (5/29) respectively." (PMID 28403223, 2017).
tumor (continued). "VEGFA is an angiogenic factor secreted by tumors, in particular those with VEGFA amplification, as well as by macrophages and lymphocytes in the tumor microenvironment." (PMID 28403223, 2017). "VEGFs have been shown to play multi-faceted roles in stimulating neo-angiogenesis and tumor growth and among the VEGFs, VEGFA, in particular, has been shown to mediate angiogenesis, a critical step in both tumor growth and metastasis formation." (PMID 28403223, 2017). "From a mechanistic perspective, MMP2, MMP12 and VEGFA, which are produced by macrophages and are important in tumor invasion and angiogenesis, are downregulated upon blockade of the CSF1/ CSF1R axis." (PMID 28467800, 2017). "VEGFA mRNA expression in MMQ tumor stem-like cells were increased 273.2% compared with MMQ cells (P < 0.01)." (PMID 28163656, 2017). "MMQ cells and tumor stem-like cells transfected with VEGFA siRNA showed efficient silencing of VEGFA expression, as evaluaed by real-time RT-PCR and immunoblot analysis." (PMID 28163656, 2017). "In summary, we have identified an association between VEGFA gene amplification in CRC and reduced macrophages, PD-1-positive infiltrating lymphocytes and PD-L1 stromal expression at the tumor front." (PMID 28403223, 2017). "In cell viability assay, tumor stem-like cells showed reduction of cell viability by VEGFA silencing compared with siControl transfected cells." (PMID 28163656, 2017). "Many tumor cell lines constitutively express and secrete VEGFA, indicating that deregulation of its expression is a common event in transformed cells." (PMID 28415573, 2017). "Pathways activated by VEGFA that increase cancer stem‐like cells and tumor initiation are largely uncharacterized." (PMID 28179359, 2017). "Our studies identify a new molecular node that connects growth factor signaling, TBP, and VEGFA expression to promote tumor development." (PMID 28415573, 2017). "The protein expression of VEGFA increased 102.3% in MMQ tumor sphere cells compared with MMQ cells (P < 0.01)." (PMID 28163656, 2017). "VEGFA-mediated angiogenesis during the epithelial-to-mesenchymal transition has been proposed as a link between cancer stemness and tumor initiation." (PMID 28060721, 2017). "The expression of VEGFA were high in tumor spheres cultured from both MMQ cell and human prolactinomas." (PMID 28163656, 2017). "MYC and VEGFA levels were also increased in metastatic colon cancer cohort compared with primary tumor, similar to RBP4." (PMID 28689994, 2017). "Of all identified molecules that lead the blood vessel formation, VEGFA appears the main molecular driver of tumor angiogenesis." (PMID 29270405, 2017). "Among the PTEN-regulated chemo- and cytokines we verified differential expression of CSF2 (also known as GM-CSF), EGF and VEGFA by tumor cells." (PMID 28008153, 2017). "Firstly, the high expression of VEGFA in MMQ tumor stem-like cells is tested in vitro, the in vivo environment is so much more complicated than in cell lines." (PMID 28163656, 2017). "MMP-9 cleaves the components in the extracellular matrix, releasing VEGFA from its sequestered state and inducing angiogenesis around the tumor, as seen in hyperplastic islet of Langerhans." (PMID 28403223, 2017). "The vascular endothelial growth factor A (VEGFA) protein is a chemical signaling molecule that plays a central role in physiological and tumor-induced angiogenesis and is also a target of antiangiogenic therapies." (PMID 27777493, 2016). "Angiogenesis is an important mechanism that sustains GBM tumor growth, and VEGFA is a key angiogenesis regulator." (PMID 27329597, 2016). "Analysis of microarray data sets (GSE5764, GSE5460 and GSE14017) found Xist was significantly reduced in tumor and metastasis samples, compared to normal tissue, and inversely correlated with a positive control VEGFA expression profile." (PMID 27248326, 2016).